MYC (MYC proto-oncogene, bHLH transcription factor)
Diseases named in the same sentence as MYC in open-access papers (continued):
Sharing a sentence is not in itself a finding about the gene and the disease.
cancer (continued). "Finally, several cancer type-specific changes in epithelial-to-mesenchymal transition (EMT) and key intracellular signaling pathways such as MYC, MTORC1, or KRAS, occurred in female and male cases with midrange TI values." (PMID 38622740, 2024). "Cancer developed faster in all transgenic mice with RAS and MYC OCGs." (PMID 38827026, 2024). "In addition, it was shown by promoter analysis that the expression of many cancer stem cell (CSC)-related genes such as TERT, BMI1, BSG (CD147), and PROM1 (CD133) was under the control of SP1, HIF1A, and MYC." (PMID 39590335, 2024). "Given the ubiquitous high expression of MYC and CREPT in various tumors, we speculate that targeting this complex could be a new strategy for anti-cancer therapy." (PMID 39615685, 2024). "The GSEA enrichment analysis of pan-cancer results indicate that CRRS may be involved in several key signaling pathways, including the MYC-TARGETS, G2M_CHEC KPOINT, E2F TARGETS etc, potentially influencing cancer progression." (PMID 39539551, 2024). "Furthermore, both entities displayed a shared regulation of genes, including MYC, PHGDH, FBXO2 and BRDT, which promote cancer progression according to previous studies." (PMID 38725048, 2024). "The MYC gene family, consisting of MYC (also known as C-Myc), MYCN (N-Myc), and MYCL1 (LMYC), plays a significant role in promoting epidermal differentiation, cell proliferation, apoptosis, and the development of specific human cancers." (PMID 38566927, 2024). "We validated them in vitro in different cancer cell lines with deregulated KRAS and/or MYC." (PMID 39457457, 2024). "Furthermore, the high CBLL1 expression observed in the tumourspheres was accompanied by the upregulation of other established cancer stem cell markers, including LGR5, NANOG, SOX2, KLF4 and c-MYC mRNA levels." (PMID 38339195, 2024). "Interestingly, while DMG samples showed significantly higher expression of MYC and its target genes compared to normal samples, PIN1 expression was lower in the cancer compared to matched normal tissue." (PMID 39093942, 2024). "Also, the oncogenic activity of MYC is significantly induced by HDAC2, suggesting the potential benefits of applying HDAC inhibitors in the prevention and treatment of Myc-driven cancers." (PMID 39063083, 2024). "Interestingly, MYC promotes the uptake of Trp through increasing the expression of the Trp transporters SLC1A5 and SLC7A5 to drive cell growth in cultured cancer cells." (PMID 38769298, 2024). "Despite lower overall ERBB2 expression, HER2-HET tumors retained levels of PI3K/ERBB pathway activation equivalent to those in non-HET/pCR cancers, likely due to increased expression of downstream pathway components including MYC and EIF4EBP1." (PMID 38300710, 2024).
cancer (continued). "High MYC expression activates the E3 ligase KLHL42, which is responsible for pRB1 ubiquitination and degradation and subsequently confers resistance to CDK4/6i to cancer cells." (PMID 38424044, 2024). "Remarkably, IGF2BP2 regulates glutamine uptake and metabolism by upregulating MYC, glutamic–pyruvic transaminase 2 (GPT2), and solute carrier family 1 member 5 (SLC1A5) in AML, demonstrating that IGF2BP2s can influence amino acid metabolism in cancer." (PMID 39596216, 2024). "In addition, multiple oncogenes, such as MYC, RAS, and PI3K, can activate rRNA transcription and boost ribosome biogenesis to support cancer cell proliferation." (PMID 39046443, 2024). "Moreover, downregulated cancer stemness proteins, including BMI1, c-MYC, and SOX2, were observed in EXOSC5 knockdown EC cells." (PMID 38164180, 2024). "Our rationally designed genome-wide CRISPR screen using a conditional MYC expression system uniquely allowed us to determine genes that are only essential to cancer cells with high, and not low, MYC expression." (PMID 38302473, 2024). "RS is a common feature of cancer cells with accelerated S-phase entry, driven by oncogene activation, such as MYC, Ras and Cyclin E, or the absence of tumour suppressors, such as RB12." (PMID 38383676, 2024). "Here, we combine a CRISPR-based genome-wide library screen with Tet system-regulated MYC expression to identify gene targets that, when genetically inactivated, are lethal to cancer cells only with high but not low MYC expression." (PMID 38302473, 2024). "XPO1 as a potential therapeutic target specifically for MYC-driven cancers has not been previously recognized." (PMID 38302473, 2024). "BTX-1188 showed cytotoxicity against a variety of cancer cell lines (such as MYC-dependent, non-MYC-dependent cell lines, and primary human AML patient samples)." (PMID 39169396, 2024). "Furthermore, P-TEFb promotes enhancer-driven transcription of MYC and MCL1 oncogenes and protein stability of MYC to underwrite cancer cell dependency on these short-lived oncogenic proteins." (PMID 37811895, 2023). "We then data mined the collection of 1001 human cancer cell lines in which we had previously obtained the DNA methylation landscapes and where sensitivity to the bromodomain inhibitor JQ1, whose activity depend on MYC activation, was also available." (PMID 37173708, 2023). "Our results show that MYC activation ablates oscillation of the LAT1 subunit and increases LAT1 total protein expression and membrane localization, corroborating previous findings of MYC-dependent upregulation of LAT1 in cancer and T cells." (PMID 37639465, 2023). "Given the pronounced links between WNT signalling, induction of MYC, and its known role as a master regulator of biogenesis, further exploration of ribosome heterogeneity in certain WNT-driven cancers may open a new therapeutic avenue." (PMID 37048063, 2023). "When a dominant negative mutant of AMPK was ectopically expressed in these cells, the expression of c-MYC was enhanced and resistant to metformin, suggesting that the AMPK–FOXO axis is recruited by metformin to suppress cancer stemness in NSCLC/PTX-resistant cells." (PMID 38068934, 2023). "MYC and PVT1 belong to the 8q24 genomic region, which is frequently altered in cancer." (PMID 36901971, 2023). "In addition to performing protein translation, ribosomes co-regulate cancer cell growth and proliferation through the RAS/RAF/MEK/ERK, MYC, and PI3K/AKT/mTOR pathways." (PMID 37745301, 2023). "We find that MYC has a relatively high median z-score, suggesting MYC levels may be broadly important for POLR3G expression in cancer." (PMID 37894362, 2023).
cancer (continued). "Indeed, cancer cells generally display elevated replication stress due to activated drivers such as CCNE1, KRAS and MYC." (PMID 37325550, 2023). "Moreover, we identified the miR-26a-1-3p site in the 3′ untranslated region (UTR) of GSK3β, MYC, and CCND1 mRNA, thus predicting a link between miR-26a and Met/GSK3β/MYC/CCND1 in cancers." (PMID 36672275, 2023). "Currently, no MYC inhibitor has been clinically established, but significant efforts are globally ongoing to realize this possibility for cancer patients." (PMID 37627164, 2023). "Moreover, we observed a positive correlation between ORC6 expression and MYC target V2, MYC target V1, MTORC1, mitotic spindle, G2 checkpoint, E2F target, DNA repair, and other pathways across cancers." (PMID 37901236, 2023). "Furthermore, for assessing the function of CORE, MYC and PAF modules in cancer cells, Nanog (for CORE module), c-Myc (for MYC module) and Ctr9 (for PAF module) were knocked down in glioma cell line U87 respectively." (PMID 37059858, 2023). "In addition, we identified recurrent CNVs in regions of well-recognized cancer-driving genes (EGFR, MTOR, CCND1, and MYC) or tumor suppressor gene (RB1), with a relatively higher variation in the DN and T stages." (PMID 36914617, 2023). "A future line of inquiry should determine if non-canonical circadian oscillations that emerge in MYC-amplified cancer cells contribute to proliferation or metabolic phenotype." (PMID 37639465, 2023). "This revealed that MTOR, and to a lesser extent RPTOR and RICTOR, are indispensable for the survival of the majority of cancer cell lines, regardless of MYC amplification status." (PMID 37642941, 2023). "In addition to MYC protein stabilization via ERK1/2 phosphorylation under normal conditions, or through ERK5 when cancer cells are treated with MEK1/2 or ERK1/2 inhibitors, our data provides a new mechanism for MYC protein regulation by KRAS oncogene." (PMID 37210549, 2023). "In order to modify critical MYC target genes or even MYC itself on the nucleotide level, CRISPR-based artificial gene regulators could be applied for targeted cancer therapy, possibly also in combination with other drugs." (PMID 36969025, 2023). "In vivo, G4 formation in the c-MYC oncogene promoter may be one of the reasons for DNA hypomethylation resulting in the overexpression of the c-MYC protein and cancer progression." (PMID 38203216, 2023). "We first detected the mRNA expression level of c-MYC in Vector, NEK8, sgNC, or sgNEK8 cancer cells." (PMID 37596667, 2023). "Even though the ecDNA landscapes of the three cancer cell types were not the same, we identified several ecDNA hotspots, such as the oncogene MYC, CDK4 and CCND1 genomic loci." (PMID 37517066, 2023). "This cluster is enriched in the Hippo signaling pathway (KEGG:04390) (Bonferroni-corrected p-value = 1.56e−3), WNT Signaling Pathway (KEGG:04310) (Bonferroni-corrected p-value = 9.57e−3) and Pathways in cancer (KEGG:05200) with genes such as BCL2L1, MYC, FOS (Bonferroni-corrected p-value = 0.047)." (PMID 38057321, 2023). "Moreover, the investigated metallohelices suppressed the expression of c-MYC and k-RAS genes at mRNA and protein levels in HCT116 human cancer cells, as revealed by RT-qPCR analysis and western blotting." (PMID 37019444, 2023). "The MYC-ER and N-MYC-ER systems model genomic amplification in cancer, where MYC is no longer under the control of endogenous promoter and other regulatory elements." (PMID 37639465, 2023).
cancer (continued). "HCC patient specimens were stained for MSI2, MYC and NANOG to test if MSI2-mediated MYC translation is TIC-specific or if non-TIC bulk cancers also show a similar tendency." (PMID 37117191, 2023). "Recent evidence has shown that inhibiting the downstream signaling of MYC through cyclin-dependent kinase (CDK) inhibitors can enhance cancer cell sensitivity to PARP inhibitors, regardless of the BRCA status, in triple-negative breast cancer (TNBC)." (PMID 37755397, 2023). "We therefore uncover a previously unknown mode of MYC destabilization by RUNX3 and provide an explanation as to why RUNX3 inhibits early-stage cancer development in gastrointestinal and lung mouse cancer models." (PMID 37400551, 2023). "However, since the RIP-seq results were also validated with real-time RT-PCR, at least six genes related to “Pathways in cancer,” i.e., TGFB2, CREBBP, EP300, FOS, JUN, and MYC were certainly affected by the hnRNPM-AS1-S interaction." (PMID 37671887, 2023). "MSI2 also maintains the self-renewal program in cancer by directly increasing the translation of MYC and other proteins, without significantly increasing their mRNA levels." (PMID 37117191, 2023). "They regulate gene expression, cancer-cell proliferation, survival, and oncogenic progression of B-cell NHL, where they might activate the MYC and BCL2 pathways." (PMID 37580826, 2023). "Third, in vitro functional assays demonstrated that knockdown of BMI1 could significantly attenuate the cancer‐promoting effect of SNHG3 overexpression, suggesting that the SNHG3/c‐MYC/BMI1 axis may play an important regulatory role in BLCa." (PMID 36208024, 2023). "In HEK293T cells—which have low MYC levels compared to cancer cells such as Ramos and BT168—Omomyc did not significantly influence MYC expression (middle)." (PMID 36830948, 2023). "Interestingly, a molecular crosstalk between c-MYC and HIF-1A has been reported in cancer progression." (PMID 37624039, 2023). "Using UVGs, we defined well-known cancer hallmarks including inflammation and cell cycle signatures, along with MYC signaling and goblet-like malignant states that were not reported in previous transcriptomic programs." (PMID 38084922, 2023). "Despite the plethora of MYC synthetic lethal targets and development of small‐molecule inhibitors against them, targeted synthetic lethality therapy against MYC‐driven cancers is still not approved for clinical use." (PMID 36684069, 2023). "MYC, SLC1A5, mTORC1, and glutaminase could be further utilized as a biomarker to recognize glutamine-addicted cancers." (PMID 37635935, 2023). "Prominently, MYC activates glutamine transporters and feeds more glutamine into the TCA cycle, resulting in the glutamine-addicted metabolic feature of many MYC-driven cancers." (PMID 37601651, 2023). "Finally, we tested the clinical consequences of combined overexpression of MYC and ST6GALNAC4 in human patients by performing a pan-cancer survival analysis of The Cancer Genome Atlas (TCGA) data." (PMID 36897988, 2023). "Moreover, MEIS1 was a directly repressed target of MYC, and via effects on HOXB13, links MYC activity to androgen receptor activity to mediate cancer development." (PMID 36836180, 2023). "Given the roles of MYC and E2F1 in regulating the production of CDCA7, it is reasonable to assume that CDCA7 may similarly prevent the ferroptosis of cancer cells." (PMID 37510310, 2023). "As KRAS induces MYC, mitochondria appear to be the primary target of KRAS and MYC in cancer." (PMID 37158894, 2023). "Therefore, it is important to elucidate the biology of the specific driver oncogenes (including MYC and BCL family genes) regulated by the Brd/BET proteins in individual cancer types." (PMID 37049806, 2023).
cancer (continued). "Overall, our data point to an MYC/PRMT5/RNAPII axis that controls termination via RNAPII symmetrical dimethylation and contributes to rewiring the expression of genes altered by MYC overexpression in cancer cells." (PMID 36830948, 2023). "Therefore, in cancer, when c-MYC levels are high, HIF and c-MYC collectively remodel cellular processes to increase oncogenic potential including angiogenesis and metastasis." (PMID 37614497, 2023). "Due to MYC’s pivotal role in human cancer, it is not surprising that many attempts have been pursued to inhibit oncogenic MYC functions including multiple approaches to interfere with its transcriptional or post-translational regulation." (PMID 36969025, 2023). "In vitro experiments suggest that the SNP is included in a region that can physically interact with the MYC promoter exclusively in cancer cells but not in normal epithelial cells." (PMID 37443779, 2023). "Furthermore, we treated cells with cisplatin, ME, or both, and the expression of cancer pathway factors was assessed, including HSP90AB1, IGF1R, p-H2AX, MYC, and PTEN." (PMID 37180757, 2023). "Beyond MYC, our POLR3G co-expression correlation survey identifies specific transcription and chromatin-related factors with even stronger correlation signatures in cancer." (PMID 37894362, 2023). "While it was shown that disruption of even one gene, crucial for MYC‐dependent cancer development can be sufficient to decrease cancer cell growth, it is still not clear which MYC targets are essential for cancer cells." (PMID 37519063, 2023). "Additionally, FBXW9 was positively correlated with the activity of MYC signaling according to RABIT transcription factor regulatory impact, which is a well-known contributor to cancer stemness." (PMID 36982338, 2023). "In addition, epithelial-mesenchymal transition, oxidative phosphorylation, unfolded protein response, MYC targets, and MTORC1 signaling are closely related to the expression of SLC1A5 in cancer." (PMID 37566748, 2023). "F. nucleatum may enhance the expression of cancer-related genes and oncogenes including STAT3, JAK1, and MYC." (PMID 37174014, 2023). "In further support of this notion, we found that 100 nM IACS-010759 treatment significantly decreased the abundance of MYC in various types of cancer cells from MYC-activated ovarian (A2780 and HEYA8), colorectal (HCT116 and SW480), and breast (MDA-MB-468) cancer cell lines." (PMID 37130865, 2023). "We next performed RNA-sequencing of each circadian time series in the three cancer cell lines with or without MYC activation, as replicates, and used the ECHO algorithm to detect oscillating genes." (PMID 37639465, 2023). "Therefore, we propose a new mechanism of ADORA2A-mediated metabolic-epigenetic cascade via the ERK/MYC/PYCR/SIRT6/7 axis in promoting lineage plasticity and resistance to targeted therapy in cancer cells." (PMID 38099497, 2023). "Recently, a screen for regulators of the levels of the transcription factor MYC by de Almeida and colleagues identified an unexpected function for human AKIRIN2 as a regulator of the turnover of a subset of nuclear proteins in human cancer cells." (PMID 37767001, 2023). "We then explored by real-time qPCR the impact of miR-662 overexpression in MDA-MB-231 cells on expression levels of well-established stemness markers that are involved in embryogenesis and cancer –NOTCH1, WNT7b, ZEB1, TCF3, CTNNB1, CD44, CD24, SNAI2, OCT-04, c-MYC, EZH2–." (PMID 37443350, 2023). "Studies have demonstrated that this compound can bind to the c-MYC and BCL-2 oncogene promoter G4s (ΔTm = 16.4 and 15.4 °C, respectively, in a FRET melting assay) and downregulate the expression of these oncogenes in cancer cells." (PMID 36979947, 2023).